NOX4 (NADPH oxidase 4)
Diseases named in the same sentence as NOX4 in open-access papers (continued):
Sharing a sentence is not in itself a finding about the gene and the disease.
tumor (continued). "For instance, upregulated NOX4 predicts poor prognosis and facilitates tumor progression in CRC." (PMID 35794979, 2022). "Of note, we have also found that targeting Nox4 in macrophages, a major component of immune cells in the stroma, did not alter the pro-tumorigenic M2 macrophage polarization or phenotype, further suggesting that CAFs are the main source of Nox4 in the tumor stroma." (PMID 35836253, 2022). "Therefore, the diverse function of NOX4 and downstream ROS production during tumor progression make it a promising therapeutic target, and it is imperative to thoroughly understand the molecular mechanisms in different cancer models." (PMID 35646942, 2022). "NOX4 appears, at least in some cases, to localize to mitochondria, where it seems to function as a sensor of mitochondrial ATP with the purpose to regulate flux through the glycolytic pathway in tumor cells." (PMID 34944680, 2021). "Animal model studies have suggested roles for NOX4 in tumor metastasis and angiogenesis." (PMID 33557266, 2021). "This important implication prompted us to further investigate factors that may modulate the effects of NOX4 in the tumor environment." (PMID 33557266, 2021). "Indeed, such an approach is currently a significant area of research with a recent study showing pharmacological inhibition of NOX4, a protein important in this conversion, reduced tumour growth in mouse xenograft models." (PMID 33580106, 2021). "We also showed high tumor NOX2 (CYBB) expression that was tightly correlated with canonical M1 and M2 markers, and likely reflects TAMs, is also closely associated with many of the same cancer promoting programs linked to NOX4." (PMID 33557266, 2021). "A significant proportion of solid cancers are CAF-rich, and combining NOX4 inhibition with immunotherapy could improve clinical outcome in these tumours." (PMID 32830198, 2020). "However, current researches on NOX4 are mainly focused on tumor cells, and the role of NOX4 in VM formation is rarely mentioned." (PMID 33153467, 2020). "It was reported that NOX4 is overexpressed in many malignancies and participates in malignant processes such as proliferation and metastasis; NOX4 can also promote tumor angiogenesis by regulating the production of vascular endothelial growth factor, which further results in poor prognosis." (PMID 33153467, 2020). "The GBC patients with high NOX4 expression in tumor cells and stroma have a poor prognosis." (PMID 33153467, 2020). "Collectively, our study firstly demonstrate that GCAFs can upregulate NOX4 expression to promote VM formation and tumor growth in GBC, which may be achieved by paracrine IL-6-mediated IL-6-JAK-STAT3 signal pathway." (PMID 33153467, 2020). "NOX4 expression is moderately increased in all thyroid tumors, which may be related to the role of the tumor stroma paracrine effect." (PMID 29478325, 2019). "They found that the enzyme NADPH oxidate 4 (NOX4), is an integral component of fibroblast differentiation and may be a viable target for inhibition of CAF-associated tumor immune evasion." (PMID 30828330, 2019). "Moreover, stromal areas with clusters of intense Nox4 staining were localized adjacent to tumor foci with abundant TGFβ staining." (PMID 29441570, 2018). "And so forth, increased NOX4/p22phox in cancer might be related to a higher proliferation rate and tumor progression." (PMID 30367082, 2018). "Interestingly, use of Nox4-specific anti-sense oligonucleotide significantly prevented the tumor growth in nude mouse xenograft model, indicating the potential for targeting this molecule." (PMID 29491408, 2018). "Tumor cells have been shown to induce TGF-β 1-dependent upregulation of NOX4 in breast stromal cells in vitro; however, to date, investigation of the role of NOX4 in cancer has predominantly focused on the tumor cell, where a variety of functional effects have been described." (PMID 28922779, 2018).
tumor (continued). "In addition, we have only examined the potential for NOX4 inhibition in the context of single-agent therapy, showing that this reduces myofibroblast accumulation and tumor growth." (PMID 28922779, 2018). "The depletion of NOX1 and NOX4 in tumor xenografts was confirmed by Western blot." (PMID 29684820, 2018). "Nox4 has been found to promote tumor progression of many types of cancer through various pathways." (PMID 30513726, 2018). "Furthermore, we show that NOX4 inhibition in CAFs can abrogate the tumor-promoting function of these cells in vitro and in vivo and that this effect can be achieved pharmacologically (using GKT137831), identifying this enzyme as a druggable therapeutic target." (PMID 28922779, 2018). "Also, immunofluorescence analysis showed that NOX4 protein was located in the cytoplasm of the untreated liver tissues and was downregulated in the pre-neoplastic nodules and tumor tissues." (PMID 27895046, 2017). "However, in a recent study in which the consequences of the ablation of Nox1,2 or 4 were assessed in a slow-growing mouse tumour model, only Nox4 was found to contribute positively to angiogenesis." (PMID 28433660, 2017). "Similarly, NOX4 promotes tumor angiogenesis through stabilization of HIF-1α and induction of VEGF expression." (PMID 28594389, 2017). "A recent report has shown the downregulation of Nox4 in mice after PH during tumorigenesis induced by DEN; the same report showed that silencing Nox4 in xenograft experiments in athymic mice conferred an advantage to human hepatocarcinoma cells, as shown by more rapid tumor formation and growth." (PMID 27895046, 2017). "Similarly, we observed that the tumours formed by NOX4-silenced cells grew at a much slower rate than control tumours." (PMID 28232723, 2017). "These authors suggested that NOX4 plays an essential role as a tumor suppressor in liver tissue." (PMID 27895046, 2017). "Gene-neighbour and gene set enrichment analyses revealed that NOX1/2/5 were strongly correlated with genes associated with cancer cell survival and metastasis, whereas increased NOX4 and DUOX1 expression was associated with genes that inhibit tumour progression." (PMID 28894215, 2017). "NOX4 promotes tumor angiogenesis by stabilization of HIF-1α and induction of VEGF expression." (PMID 28594389, 2017). "Thus, our data show that NOX4 protein expression decreases in vivo in preneoplastic lesions and tumor tissue." (PMID 27895046, 2017). "The downregulation of Nox4 during early stages of carcinogenesis likely favors tumor development." (PMID 27895046, 2017). "The incapability of our 47-6 antibody to detect mouse or rat NOX4 may prove opportune in the context of implanted human tumor studies, providing the ability to isolate NOX4 enzymatic changes from host contamination." (PMID 28578276, 2017). "Interestingly, it has been recently reported that low NOX4 expression is an independent predictor of both shorter relapse-free survival and shorter overall survival by using immunohistochemistry in tumour tissue from 227 HCC patients." (PMID 27941881, 2017). "Furthermore, IHC staining indicated that NOX4 levels were also elevated in PDAC tumours from iKras; p53L/+ mouse model than in histologically normal pancreata from control mice." (PMID 28232723, 2017). "Moreover, tumour NOX4 and NOX2 expression was markedly higher and lower, respectively, compared to that in the normal controls, the NOX2 mRNA level was the highest among the NOX family genes." (PMID 28894215, 2017). "Nox2 and Nox4 are both induced in response to TGFβ in certain cell types, but interestingly, we did not observe upregulation of Nox2 mRNA in muscle in our previous studies using human tumor cells in athymic nude mice." (PMID 29312148, 2017).
tumor (continued). "Conversely, NOX4 shRNA-transfected A549 cells produced smaller tumors compared with scramble, and additional IL-6 administration could significantly rescue tumor growth." (PMID 25504436, 2015). "NOX4 down-regulation (knockdown efficacy was 60-70% as assessed by western blotting) by instillation of siRNA combined with atelocollagen produced a significant decrease in the tumor area in the orthotropic implantation mouse experiment." (PMID 22032647, 2011). "Importantly, we have also demonstrated that Nox4 and ROS are crucial mediators in cycling hypoxia-promoted tumor growth." (PMID 21935366, 2011). "Blockage of ROS production via Nox4 shRNA or Tempol treatment inhibits endogenous tumor microenvironment or exogenous cycling hypoxia-mediated tumor growth, suggesting that ROS play crucial roles in the promotion of tumor growth induced by cycling hypoxia." (PMID 21935366, 2011). "Based on these data, we hypothesized that Nox4 might be a critical mediator of cycling hypoxia-mediated ROS generation and tumor progression in GBM." (PMID 21935366, 2011). "Furthermore, we further explored the effects of NOX4 on the ability for tumor cell migration." (PMID 37670970, 2023). "Taken together, these results support the hypothesis that NOX4 promotes tumor growth in HCC." (PMID 37626693, 2023). "Therefore, we speculate that NOX4, as the main source of endogenous ROS production and oxidative stress, affects tumor cell glycolysis through the ROS-activated YAP pathway." (PMID 37670970, 2023). "By inhibiting miR-944/NOX4, the tumor-promoting impact of ciRS-7 could be prevented." (PMID 36672755, 2022). "For example, two recent reports noted relatively higher stromal NOX4 expression in myofibroblasts and fibroblasts adjacent to cancer cells in several types of solid tumors and suggested therapies targeting stromal NOX4 could reduce tumor growth." (PMID 33557266, 2021). "Importantly, NOX4 localization seems to be crucial for its effects as tumor suppressor." (PMID 34571961, 2021). "Therefore, we investigated whether the expression of THBS2, FSTL3, TNNT1, BGN, CTHRC1, and NOX4 was correlated with immune cell infiltration levels in CRC via the Tumor Immune Estimation Resource (TIMER) database." (PMID 35127707, 2021). "Nox4−/− or Nox2−/− mice, EC-specific Nox4, dominant-negative Nox4 or EC-specific catalase-overexpressing mice reveal that Nox2 or Nox4 or their regulators are required for ROS-dependent angiogenic signaling in ECs, tumor angiogenesis as well as post-ischemic neovascularization using a PAD model." (PMID 32781794, 2020). "Importantly, immunoblot from tumor tissues demonstrated that the suppression of ATF3/NOX4 axis in IFI6-overexpressed cells while this effect was reversed by phenformin treatment, validating the effect of IFI6-mediated OXPHOS efficiency on ATF3/NOX signaling pathway." (PMID 32727517, 2020). "Thus, whether OA-enhanced metastasis in different tumor types is dependent on individual genes, such as ANGPTL4 and NOX4, or if tumor metastasis relies on reciprocal regulation of OA-responsive genes is an interesting pursuit." (PMID 32641980, 2020). "In vitro studies herein illustrate the physiological relevance of elevated stromal Nox4 in PCa and demonstrate its role as a central mediator of (i) reciprocal epithelial‐stromal cell crosstalk, (ii) fibroblast activation and (iii) stromal‐driven tumor (cell)‐promoting hallmarks." (PMID 29441570, 2018). "Nox4 may induce cancer cell progression through promoting tumor angiogenesis." (PMID 30513726, 2018). "However, whether NOX4 could also regulate other cellular processes that occur later in progression and that favour tumour metastasis, such as migration and invasion, remains unknown." (PMID 27941881, 2017).
tumor (continued). "A following study showed that VEGF mediates CD146 dimerization and downstream signaling in a NOX4-dependent manner, which aroused our interest on the association between CD146 and VEGF pathway and finally led to the important finding that CD146 is a co-receptor of VEGFR-2 in tumor angiogenesis." (PMID 24756564, 2014). "Furthermore, NOX4 overexpression could significantly shorten the survival time of A549 and H460 tumor-harbored mice." (PMID 24946933, 2014). "Compared with normal controls, the relative mRNA expression levels of NOX4, SCD, and TIMP1 were significantly higher in tumor tissues, while those of AQP8 and NR5A2 were significantly lower." (PMID 41438584, 2026). "NOX4 has been shown to mediate resistance to EGFR-targeted therapies, while both EGFR and PDGFR are critical in signaling pathways that drive tumor growth and metastasis." (PMID 41562694, 2026). "Consistent with the transcriptomic findings, immunohistochemistry confirmed higher expression of NOX4, CXCL1, CDKN2A, and SIX1 in CRC tissues than in paired adjacent non-tumor tissues." (PMID 42317343, 2026). "Clinically, high NOX4 and IL-8 correlate with poorer responses to anti-PD-L1 therapy, while dual inhibition of NOX4 (with GKT137831) and EGFR has shown enhanced tumor suppression in mouse xenograft models." (PMID 39941826, 2025). "Additionally, it may modulate the microenvironment, thereby promoting the onset and progression of cancer, indicating that a high expression of these two cellular senescence markers, CD34 and NOX4, in endothelial cells, could be potential markers for tumor development." (PMID 39859485, 2025). "NOX4, a member of the NADPH oxidase enzyme family, constitutes a principal source of reactive oxygen species (ROS) that modulate tumor cell proliferation, migration, and invasion." (PMID 41346575, 2025). "Accordingly, NOX4/NOX1 dual inhibition impairs CAF functions in vitro and reduces tumour burden in preclinical in vivo models of iCCA." (PMID 40820091, 2025). "To confirm the expression of NOX4 in CAF from iCCA we carried out immunohistochemical analysis and staining for different markers of tumour cells and CAF." (PMID 40820091, 2025). "Use of a dual NOX4/NOX1 inhibitor impaired CAF actions and reduced tumour growth in vitro and in two different in vivo iCCA experimental models." (PMID 40820091, 2025). "This potential, together with the lack of information about the role and therapeutic potential of NOX4 in iCCA tumour cells and TME, makes NOX4 the ideal candidate." (PMID 40820091, 2025). "NADPH oxidase 4 (NOX4), a member of the NOX family, is central to the production of reactive oxygen species (ROS), which play a role in tumor cell proliferation, apoptosis, and various biological functions." (PMID 39991587, 2025). "NOX2, NOX4, and NOX5 mRNA levels increased with tumor progression stages, while NOX1 and DUOX1 expression decreased in more advanced stages." (PMID 38542437, 2024). "DUSP1 expression was decreased in tumor tissue whereas TNF, NOX4, and LONP1 expressions were increased in tumor tissue, compared with those in normal tissue." (PMID 38758860, 2024). "Inactivation of MYC by Tet consistently diminished NOX4 induction in P493 cells, confirming that MYC family oncoproteins specifically stimulate NOX4 expression in human tumor cells." (PMID 38493213, 2024). "Using narrow-down analysis, six tumor antigens (AGPS, NRAS, MTDH, PANX1, NOX4, and PPARD) were found to be related to better prognoses as well as the infiltration of antigen-presenting cells in LUAD." (PMID 38331967, 2024). "In summary, the reduction of NOX4-derived H2O2 by DPI or NAC, or the attenuation of AQP3 as the ROS transport channel, led to a decrease in tumor cell metastasis to the lungs." (PMID 38230207, 2024).
tumor (continued). "In both malignant and benign thyroid tissue, the production of ROS and expression of the NADPH oxidase 4 (NOX4), a significant source of ROS, playing an important role in tumor cell proliferation and apoptosis, were found to be higher than in healthy tissues." (PMID 37697017, 2024). "Considering the interaction between tumor antigens and APCs, these potential antigens were further screened through the TIMER database where it was found that AGPS, NRAS, MTDH, PANX1, NOX4, and PPARD genes were positively correlated with different APCs." (PMID 38331967, 2024). "In this work, we discovered that MYC orchestrated the crosstalk of two parallel metabolic pathways, the NOX4-ROS pathway and the PLK1-NUDT1 nucleotide-sanitizing pathway, to promote tumor cell survival." (PMID 38493213, 2024). "The key concept emerging from our data is that MYC finely coordinated two metabolic processes that act in parallel, the NOX4-ROS pathway and the PLK1-NUDT1 nucleotide-sanitizing pathway, to maintain tumor cell survival." (PMID 38493213, 2024). "Recently, CHAC1 and NOX4, along with GPX4, have been suggested to be hallmarks of ferroptosis in tumor cells." (PMID 37371096, 2023). "The expressions of NOX4 and FKBP10 were significantly higher in STAD tumor tissues than those in the paired adjacent normal tissues, respectively (all P < 0.05)." (PMID 36915111, 2023). "Functionally, NOX4 knockdown inhibits HCC cell proliferation and tumor development in xenograft animal models while NOX4 overexpression promotes tumor progression, suggesting that NOX4 plays an oncogenic role in the growth of HCC." (PMID 37626693, 2023). "Higher expressions of NOX4 and FKBP10, and lower expressions of ALDH3A2 and MAOA were observed in tumor samples compared with the normal tissues, respectively." (PMID 36915111, 2023). "Subsequently, this study further investigated the relationship between NOX4 expression in HCC and patients’ survival, as well as the effects of NOX4 over/down expression in vitro migration, proliferation, and in vivo tumor growth." (PMID 37626693, 2023). "A mechanism of tumor cell death is proposed based on our findings where oxidative stress is induced by NCX4040 from simultaneous induction of NOX4, TNF-α and CHAC1 in tumor cell death." (PMID 36612280, 2022). "This positive feedback system demonstrates the capacity of OC cells to utilize the overproduction of NOX4-derived ROS to activate HIF-1α and VEGF and promote angiogenesis and tumor growth." (PMID 35743145, 2022). "Overall, our protein data and our in silico analysis show that NOX4 is mainly expressed in GBM transition and stem cells, and its expression is lower in the bulk differentiated tumour cells." (PMID 35203105, 2022). "NOX4 is abundantly expressed in NSCLC tissues and contribute to tumor development through diverse oncogenic mechanisms." (PMID 35646942, 2022). "The NOX family, which includes NOX1, NOX2, NOX3, NOX4, and NOX5 subtypes, is a key mediator of cyclic hypoxia-mediated ROS production and tumor progression." (PMID 36278207, 2022). "Besides, NOX4-induced ROS could also elevate cytokine production via PI3K/Akt signaling-dependent manner to increase tumor-associated macrophage infiltration and exert pro-tumor function in NSCLC." (PMID 35646942, 2022). "Precious study has revealed that NOX4 expression in RCC tissues mediates the expression and activity of hypoxia-inducible factor 2α (HIF-2α), a crucial transcriptional factor of tumor glycolysis and various malignant behavior, to support renal tumorigenesis." (PMID 35646942, 2022). "Another study in NSCLC showed that NOX4-derived ROS from NSCLC cells stimulate PI3K/AKT signaling-dependent production of cytokines and chemokines leading to recruitment of tumor-promoting M2 macrophages." (PMID 36670929, 2022). "NADPH oxidase 4 (NOX4), a member of the NOX family, is an important source of reactive oxygen species and plays an important role in tumour cell proliferation and apoptosis." (PMID 35719914, 2022).